CD4 (CD4 molecule)
Diseases named in the same sentence as CD4 in open-access papers (continued):
Sharing a sentence is not in itself a finding about the gene and the disease.
HIV-1 infection (continued). "And finally, a number of clinical parameters of HIV-1 infection like the time since self-reported first positive HIV test, antiretroviral therapy status and duration, CD4 count, and the proportion gp41 ambiguous base pairs corroborated the reported order of infection events." (PMID 22615999, 2012). "To analyze the effect of the duration of HIV-1 infection and aging process on the T cell immune response, we assessed T cell differentiation and senescence (CD28+, CD57+, and CD57+CD28−) of both CD4+ and CD8+ T cells in two perinatally HIV-1 infected age groups on cART." (PMID 23029209, 2012). "On the other hand, Nef has been implicated as a major determinant of killing of non-infected CD4+ T-lymphocytes in HIV-1 infection of tonsil histocultures and, much more prominently, in humanized mice." (PMID 23227982, 2012). "HIV-1 infection of resting CD4+ T cells is nonproductive due to multiple blocks in the viral life cycle." (PMID 23170164, 2012). "The amount of 3TC we applied seems to block HIV-1 infection, as neither CD4 T cell depletion nor CD4 T cell activation were observed in these tissues." (PMID 23236398, 2012). "Several studies on peripheral blood mononuclear cells (PBMC) have found that APOBEC3G mRNA levels correlate positively with the CD4 count and negatively with the viral load of untreated HIV-1-infected subjects, suggesting that APOBEC3G contributes to the control of HIV-1 infection." (PMID 22479480, 2012). "It has been known for over two decades that quiescent/resting CD4+ T-cells are highly refractory to HIV-1 infection, particularly to post-entry infection of R5-tropic, but not to X4-tropic viruses since resting CD4+ T-cells express the HIV-1 co-receptor CXCR4." (PMID 23092163, 2012). "A close link between CD4+ T cell depletion and increased blood IL-7 levels has been demonstrated in HIV-1 infection and in other, non-HIV related conditions of lymphopenia possibly reflecting the decreased IL-7 consumption associated with the loss of T cells." (PMID 22194871, 2011). "In the current study, we address the question of whether HIV-1 infection accelerates the aging process by characterizing the effects of HIV-1 infection and aging on the naïve CD4+ T-cell compartment." (PMID 21298072, 2011). "The data presented here are novel in that they prove that both Bacitracin and DTNB (besides acting on cell PDI), are also virucidal agents against T-tropic HIV-1 infection, and DTNB acts not only at early viral cycle stages but also at late stages with long lasting effects on the CD4 cells." (PMID 21435237, 2011). "The data presented here were novel in that they proved that bDLE acted by inhibiting HIV-1 infection through protection of the host target CD4 cells at noncytotoxic levels." (PMID 22044844, 2011). "In the early stages of HIV-1 infection, the viral protein HIV-1 Nef, reported toaccelerate CD4 down-regulation, avoiding viral superinfection and promotingefficient viral spread and optimal viral particle production, also alters theintracellular trafficking of MHC-I and MHC-II molecules." (PMID 21533244, 2011). "Our results demonstrate that the negative effects of HIV-1 infection and aging on naïve CD4+ T-cells are predominantly additive." (PMID 21298072, 2011). "This guarantees that only cells containing the suicide vector would be permissive for HIV-1 infection, thereby eliminating the possibility of virus replication in HeLa SS6 cells only transfected with a CD4 expression plasmid if a co-transfection approach using separate plasmids would have been used." (PMID 21223573, 2011). "More relevant to the pathogenesis of HIV-1 infection, we demonstrated that the H2O2-mediated induction of DCIR and apoptosis is coupled with an increased virus binding/entry and higher replication of HIV-1 in CD4+ T cells." (PMID 21085612, 2010).
HIV-1 infection (continued). "Second, while we recognize that B-cells are not natural targets for HIV-1 infection, Raji/CD4 cells can be infected by both HTLV-1 and HIV-1 vectors for comparative analyses." (PMID 20195464, 2010). "We screened a library of isoxazolidine and isoxazole sulfonamides and found four compounds that inhibited HIV-1 infection in human CD4+ lymphocytic T cells with no toxicity at IC90 concentrations." (PMID 20486932, 2010). "This contrasts with the previous reports on the effect of HIV-1 infection on TCRζ expression in patients not receiving cART in which there was a correlation with CD4 counts and an inverse correlation with viral loads." (PMID 20224795, 2010). "These resting cells carrying a non-productive HIV-1 infection, derived from infected CD4+ lymphoblasts that have reverted back to a resting memory state and show a specific pattern of surface markers (including CD4+and HLA DR−)." (PMID 19564922, 2009). "The infected GALT consequently serves as the major reservoir for HIV-1 infection and could constantly shed HIV-1 and CD4+ T cells into the intestinal lumen." (PMID 19799780, 2009). "In contrast to their study, our results do not support a role for APOBEC3G in restricting HIV-1 infection of quiescent unstimulated human CD4+ T-cells." (PMID 19300495, 2009). "In subjects with long-term non-progressive HIV-1 infection HIV-1-specific CD4+ T cell responses are typically present; in contrast, they are progressively lost in subjects with progressive infection and high levels of viral replication." (PMID 19352428, 2009). "The similarity between the effects of 191 and sCD4 on HIV-1 infection of CD4+ and CD4− cells suggested that 191 may also induce transiently activated intermediate states in the HIV-1 envelope glycoproteins." (PMID 19343205, 2009). "We hypothesize that during HIV-1 infection, HIV-1 free virus and infected/uninfected CD4+ T cells constantly shed from GALT into the intestinal lumen and are discharged with feces." (PMID 19799780, 2009). "Collectively, these results suggest that rats that express human CD4, CCR5, CycT1, and CRM1 may provide the basis for a good model system that supports multiple cycles of HIV-1 infection." (PMID 19435492, 2009). "We showed that CD81 downregulation decreased virus production by 3-fold and the resulting virus was more infectious, suggesting that CD81 tetraspanin incorporation is able to modulate HIV-1 infection, as this was recently proposed for HIV-1 infected CD4+ activated lymphocytes." (PMID 19284574, 2009). "More significantly, we demonstrated that R88-A3G expression efficiently inhibits HIV-1 infection in CD4+ cells and human PBMCs, regardless of the presence of Vif." (PMID 18414671, 2008). "This suggests that cell culture conditions, not HIV-1 infection per se, resulted in this observed up-regulation of CD4 on the surface of CD8+ T-cells." (PMID 18923697, 2008). "We did not detect subsequent changes in the CD4+ or viral load among a subset of this cohort who were observed for acquisition HSV-2 subsequent to HIV-1 infection." (PMID 17957262, 2007). "The cause and implications of these profound quantitative and qualitative changes in CD4+ memory T cell subsets during HIV-1 infection are still not well understood." (PMID 17465678, 2007). "In chronic HIV-1 infection both broad and narrow high frequency CTL responses have been seen in patients whose CD4+ T cell counts are rapidly declining, or who are at late stage disease, as well as in asymptomatic patients with stable CD4+ T cell counts and low levels of viremia." (PMID 17311088, 2007). "HIV-1 infection results in a significant increase in cellular activation, which has been shown to be of prognostic value in predicting the rate of CD4+ T cell decline without therapy." (PMID 17147468, 2006). "These cells can play a role in host immune defence, but CD4+ immune cells are also target cells for the HIV-1 virus, and their increased numbers could promote HIV-1 infection." (PMID 16740164, 2006).
HIV-1 infection (continued). "In chronic HIV-1 infection, STI studies showed only marginal, if any, improvements of HIV-1 viremia control following a number of treatment interruptions cycles, despite at least transient increases in HIV-1-specific CD8+ and CD4+ T cell responses." (PMID 15526059, 2004). "Nonetheless, systemic HIV-1 infection may still be mediated by DCs capturing inoculating HIV-1 for transport to the draining lymph nodes, where HIV-1 antigen presentation and infection of resident, activated CD4 + T cells occurs almost simultaneously." (PMID 40408432, 2025). "It turns out that T cell activation and HIV-1 infection are necessary for the formation of NEIs, as these nuclear membrane subdomains are absent in quiescent T cells, in the absence or presence of HIV-1 infection, as well as in uninfected activated CD4+ T cells." (PMID 40366329, 2025). "Unlike HIV-1 infection of CD4+ T cells, which results in the massive release of new viral particles and cell death, HTLV-1 infection induces rapid cessation of viral particle production and promotes CD4+ T-cell proliferation, transformation, and immortalization." (PMID 40004025, 2025). "However, ART does not eliminate HIV-1 infection and persistent viral reservoirs of long-lived memory CD4 + T cells harboring integrated HIV-1 proviruses represent the main obstacle to achieving a cure." (PMID 40473838, 2025). "In contrast, a recent study observed colocalization of CPSF6 with nuclear speckles in primary CD4+ T cells even in the absence of HIV-1 infection, indicating that CPSF6 may undergo less dramatic changes in localization following infection of this cell type." (PMID 41385587, 2025). "Notably, human monocytes and macrophages express CD4, unlike the mouse, serving as an important target for HIV-1 infection." (PMID 39935459, 2025). "However, depletion of these host factors in primary CD4+ T cells seem to have no or even the opposite effect on HIV-1 infection suggesting a difference in the actin cytoskeleton dynamics of these cell types." (PMID 40029073, 2025). "Furthermore, it has been reported that both CD4+ cytotoxic T lymphocytes (CTLs) and CD8+ CTLs expressing GNLY, GZMB, PRF proteins exhibit antimicrobial activity against intracellular bacteria and in HIV-1 infection." (PMID 40264781, 2025). "Importantly, despite the accumulation of somatic mutations, the three key amino acids, Trp50HC, Asn58HC, and Arg71HC, that make critical contacts with the CD4-BS of Env, remained unaltered, similar to what occurs during the affinity maturation process of VRC01-class bnAbs during HIV-1 infection." (PMID 39240111, 2024). "An increase in MM was associated with heightened sensitivity of CD4+T cells to pyroptosis, even in early differentiated and inactivated CD4+T cells, in patients with HIV-1 infection, regardless of whether patients were on antiretroviral therapy or not." (PMID 38267841, 2024). "Furthermore, subsequent co-culture of basolateral detached DCs derived from HIV-exposed IEDC with target cells resulted in HIV-1 transmission to U87.CD4.CCR5 cells through cell-cell contact, which underscores the productive HIV-1 infection of basolateral DCs upon apical viral exposure." (PMID 39729509, 2024). "Since we showed that R5/X4 and X4 viruses are very efficiently cell-to-cell transferred to macrophages, infected naïve CD4+ T cells could then transfer CXCR4-using viruses to tissue macrophages, thereby contributing to dissemination at later stages of HIV-1 infection." (PMID 38400063, 2024). "It is important to note that these markers are not exclusive to B cells and that HIV-1 infection of CD4 T cells might shift expression such that these infected cells might be T cells." (PMID 37325659, 2023). "Without the local accumulation of CD4, HIV-1 infection may be insufficient, as observed in the HIV-1 infection of vimentin-deficient cells." (PMID 37376566, 2023).
HIV-1 infection (continued). "Indeed, HIV-1 infection of resting naïve CD4+ T cells results in an abortive non-replicative infection, whilst either mitogenic or anti-CD3/CD28 mediated stimulation of T cells drives production of replicating virus." (PMID 37006246, 2023). "Since HIV-1 infection is characterized by a strong inflammatory environment, tissue disruption, and upregulation of TLR7 in CD4+ T cells, we wondered whether the TLR7/IRF-5 pathway was involved in impairing memory CD4+ T cell homeostasis during HIV-1 infection." (PMID 37227774, 2023). "Therefore, the reduction in the permissivity to HIV-1 infection of these CD4+ T cells appears to be independent of the viral tropism." (PMID 35682862, 2022). "In human CD4+ T cells, GPI-10E8 and its bifunctional derivatives were capable of fully blocking infections of diverse HIV-1 strains regardless of their tropism and the modified cells displayed a robust selective survival advantage over unmodified cells following HIV-1 infection." (PMID 34821542, 2022). "According to our previous studies, nonreprogrammed CD8+ T cells from HIV-1 noncontrollers on ART had a poor capacity to counteract HIV-1 infection when cocultured with infected CD4+ T cells; in contrast, reprogramming strongly improved the capacity of CD8+ T cells to suppress HIV-1 infection." (PMID 35380989, 2022). "In addition, the application of these TALENs directly to primary CD4+ T cells and CD34+ hematopoietic stem cells (HSCs) of infected individuals could create an immune system resistant to HIV-1 infection." (PMID 35628210, 2022). "While HIV-1 infection directly reprograms T cells to gain core features shared across human TRM populations in vivo, these virus-induced cells might still reveal functional differences from the host’s various subsets of “native” CD4+ TRM cells." (PMID 35417711, 2022). "Second, many studies have been performed in epithelial model cell lines such as HeLa, which may not accurately represent the trafficking pathways active in CD4+ T cells, the main targets for HIV-1 infection in vivo." (PMID 35770989, 2022). "Previously reported inhibitory effects on HIV-1 infection upon depletion of the HIV-1 capsid-interacting CPSF6 in cell lines and primary macrophages were ∼threefold, suggesting that the dependency of HIV-1 infection on CPSF6 is particularly high in resting CD4+ T cells." (PMID 34949807, 2022). "Data shown that HIV-1 infection does not alter the CD3+ CD4+ and CD3+ CD8+ ratios." (PMID 35307031, 2022). "Since this promoting effect is observed in multiple viral strains (NL4-3, CC_CH077 and TF_CH077) and multiple cell lines (Jurkat and SupT11 cells) as well as primary human CD4+ T cells, the promotion of HIV-1 infection by IFN-α is not specific for certain viral strains or CD4+ T cell lines." (PMID 35468127, 2022). "No information on the potential effect of CH25H on HIV-1 infection of human CD4+ T cells is currently available, although the original description of its antiviral activity was reported against mitogen-stimulated primary lymphocytes of monkeys infected with SIV." (PMID 35328442, 2022). "While both HR-EC and LR-EC have normal CD4+ T cell counts in blood, HR-EC showed a more limited number of viral blips, and had been infected with HIV-1 for a significantly longer time, suggesting that HR-EC represent a more definitive example of superior control of HIV-1 infection." (PMID 36569826, 2022). "Furthermore, profound CD4+ T lymphopenia and immune activation in the absence of HIV-1 infection among patients with malaria has been demonstrated." (PMID 34220854, 2021). "While CCR5 co-expression had no impact on the potency of CD4-GpA-RBCs, co-expression of CCR5 lowered the neutralization activity of CD4-CCR5-RBCs by almost 3-fold in comparison to CD4-RBCs, implying that HIV-1 infection of RBC viral traps was not required for potent neutralization." (PMID 33723514, 2021).
HIV-1 infection (continued). "Sterile alpha motif and HD domain-containing protein 1 (SAMHD1) is a deoxynucleoside triphosphate triphosphohydrolase (dNTPase) that restricts human immunodeficiency virus type 1 (HIV-1) infection in nondividing cells of myeloid lineage and resting CD4-positive (CD4+) T cells." (PMID 33177202, 2021). "However, these pioneering studies demonstrated that DCs can transmit a vigorous HIV-1 infection to bystander CD4+ T cells in the absence of productive viral replication on DCs, a mechanism of viral cell-to-cell transmission known as trans-infection." (PMID 35055987, 2021). "The massive HIV-1 infection of gastrointestinal CD4+ T cells leads to a weakened mucosal barrier, resulting in microbial translocation and persistent systemic immune activation during the chronic but not early stage of HIV-1 infection." (PMID 33924786, 2021). "To elucidate CD4CAR mediated HIV-1 infection, we transduced HOS.CCR5 or HOS.CXCR4 cells that are not susceptible to HIV-1 due to the lack of CD4 expression with lentiviral vectors expressing the CD4CAR or D1D2CAR and then infected them with either R5 tropic HIVNFNSXSL9 or X4 tropic HIVNL4-3." (PMID 33793675, 2021). "Notably, such a positive relationship between higher BMI levels and CD4+ counts is also described in the absence of HIV-1 infection." (PMID 34291061, 2021). "In contrast to CD4-VLPs that have short in vivo half-lives, RBC viral traps could persist in vivo for months, implying the RBC approach has the potential to provide sustained control of HIV-1 infection." (PMID 33723514, 2021). "However, the phenotypic characteristics of platelet-CD4+ T cell aggregates during HIV-1 infection has not been fully defined." (PMID 34987521, 2021). "Furthermore, among those with an HIV-1 infection, the APRIL levels were positively associated with both the CD4+ T-cell count (r = 0.2918, p = 0.0225) and CD4/CD8 ratio (r = 0.3236; p = 0.0132) but not the CD8+ T-cell count." (PMID 32850873, 2020). "Upon HIV-1 infection, MDM secrete a pool of cytokines and chemokines, which attract CD4+ T target cells, potentially creating an ideal situation for viral dissemination, and DCs may assist in viral latency induction in CD4+ T cells during cell-cell HIV-1 transfer." (PMID 32354203, 2020). "HIV-1 infection in VNPs resembles simian immunodeficiency virus (SIV) infection of natural hosts like sooty mangabeys (SMs) and African green monkeys (AGMs) in that chronically infected SM and AGM maintain stable CD4+ T cell counts despite a high level of viral replication." (PMID 32194543, 2020). "Thus, host CD4+ T cells are not intrinsically refractory to HIV-1 infection with R5 or X4-tropic viruses, and that host CD8+ T cells are effective in suppressing viral replication ex vivo." (PMID 32024974, 2020). "Moreover, during HIV-1 infection of primary CD4+ T cells, it has been reported that either cGAS is not essential for IFN induction, or significant IFN levels are not even induced." (PMID 31968566, 2020). "All over, the pattern we detected could contribute to explain why ART initiation even in primary HIV-1 infection does not fully revert the metabolic CD4 + T cells back to normal." (PMID 33298174, 2020). "This may be because the transfection efficiencies (35 to 40%) were higher than HIV-1 infection rates (10 to 15%) in CD4/CXCR4/CCR5 cells (data not shown)." (PMID 32127461, 2020). "Analyses of spreading HIV-1 infection in the SupT1 stable LEDGF KO cell lines showed an HIV replication defect, corroborating the previously reported replication delays in TALEN-edited Jurkat cells and in other human CD4+ T cell lines with a stable shRNA-mediated knockdown." (PMID 30787394, 2019). "Furthermore, the function of natural killer (NK) cells appears more well-preserved during asymptomatic HIV-2 compared with HIV-1 infection, whereas the functionality of these cells seem to drop to levels found during HIV-1 infection with declining CD4+ T-cells." (PMID 31484562, 2019).